GBGT1 (globoside alpha-1,3-N-acetylgalactosaminyltransferase 1 (FORS blood group))
Description:
Has lost the ability to synthesize Forssman glycolipid antigen (FORS1/FG). Might have acquired an alternative function in glycosphingolipid metabolism, but it remains to be established. It appears to have drifted more slowly than confirmed pseudogenes in the glycosyltransferase 6 family, suggesting that it has remained under evolutionary pressure.
Synonyms: UDP-GalNAc; A3GALNT; MGC44848; FS; UNQ2513
Tractability: Antibody: UniProt predicts a signal peptide or a membrane-spanning region.
Gene: Protein-coding gene on chromosome 9 (133,152,938 to 133,164,245, reverse strand). Ensembl gene ENSG00000148288.
Subcellular location: Golgi apparatus membrane
Gene Ontology:
Molecular function: globoside alpha-N-acetylgalactosaminyltransferase activity; hexosyltransferase activity
Biological process: glycolipid biosynthetic process; carbohydrate metabolic process
Cellular component: Golgi apparatus; vesicle; Golgi membrane; membrane
Genetic constraint (gnomAD): Loss-of-function variants: 16 observed, 19.52 expected, observed/expected ratio (o/e) 0.82, 90% interval 0.55 to 1.25. The upper end of that interval is the gene's LOEUF score, 1.25, which puts it in group 5 of 6, group 1 being the genes least tolerant of losing a copy. Missense variants: 399 observed, 433.73 expected, observed/expected ratio (o/e) 0.92, 90% interval 0.85 to 1. Synonymous variants: 158 observed, 175.34 expected, observed/expected ratio (o/e) 0.9, 90% interval 0.79 to 1.03.
Homologues: Orthologues: chimpanzee GBGT1 (98% identical), dog GBGT1 (84% identical), pig GBGT1 (81% identical), guinea pig GBGT1 (80% identical), mouse Gbgt1 (79% identical), zebrafish gbgt1l4 (43% identical), zebrafish gbgt1l3 (43% identical), zebrafish gbgt1l5 (42% identical), zebrafish gbgt1l8 (42% identical), zebrafish gbgt1l6 (41% identical), zebrafish gbgt1l2 (41% identical), zebrafish gbgt1l7 (39% identical), and 2 more. Paralogues in human: ABO (43% identical), A3GALT2 (33% identical), GLT6D1 (27% identical).
Diseases named in the same sentence as GBGT1 in open-access papers:
GBGT1 is named in the same sentence as 7 diseases in open-access papers, as found by Europe PMC text mining. Sharing a sentence is not in itself a finding about the gene and the disease. The quoted sentences say what the papers report.
Hepatitis C (1 paper, 2024). "Interference with many signaling pathways, such as NOD-like receptor signaling pathway, Herpes simplex infection, Hepatitis C, PI3K-Akt signaling pathway, and many factors, such as Atp13A4 and Gbgt1, affect the proliferation and apoptosis of 3T3-L1 preadipocytes." (PMID 39123503, 2024).
inflammatory bowel disease (1 paper, 2014). A spectrum of small and large bowel inflammatory diseases of unknown etiology. "This is a novel finding and expands on a previous study reporting that GBGT1 is differentially methylated and associated with inflammatory bowel disease." (PMID 25294702, 2014). "Although differential methylation of GBGT1 has been associated with inflammatory bowel disease and GBGT1 nonsense and inactivating missense mutations have been identified that produce a truncated or enzymatically inactive enzyme, it is not understood how GBGT1 expression is regulated." (PMID 25294702, 2014).
ovarian carcinoma (1 paper, 2014). A malignant neoplasm originating from the surface ovarian epithelium. "To this aim we analyzed the methylation levels of GBGT1 using the publicly accessible data from The Cancer Genome Atlas (TCGA) ovarian cancer sample set." (PMID 25294702, 2014). "The major finding from the present study is DNA methylation is one mechanism by which GBGT1 expression is regulated in both ovarian cancer cells and tissue." (PMID 25294702, 2014). "Bioinformatic analysis of GBGT1 in The Cancer Genome Atlas ovarian cancer dataset demonstrated that this inverse correlation was also found in primary ovarian cancer tissue samples confirming our cell line-based findings." (PMID 25294702, 2014). "The preferential expression of GBGT1 in ovarian cancer cell lines was fully confirmed in an additional set of independent experiments." (PMID 25294702, 2014). "Bisulfite sequencing therefore showed a strong inverse correlation between GBGT1 expression and DNA methylation (r = −0.86; Pearson correlation), indicating that the majority of ovarian cancer cells have silenced GBGT1 expression through DNA methylation." (PMID 25294702, 2014). "Interestingly, a correlation between GBGT1 repression and DNA hypermethylation was notably not only found in ovarian cancer cell lines." (PMID 25294702, 2014). "The present study shows that (i) GBGT1 is the most differentially expressed glycogene involved in the biosynthesis of Fs antigen and (ii) that GBGT1 expression is silenced through DNA hypermethylation in ovarian cancer cells and tissue but re-activated by 5-Aza treatment." (PMID 25294702, 2014). "GBGT1 expression is epigenetically silenced through promoter hypermethylation in ovarian cancer." (PMID 25294702, 2014). "We investigated whether the expression level of GBGT1 differs between ovarian cancer and normal ovarian surface epithelial cells." (PMID 25294702, 2014). "Bisulfite- and COBRA-analysis of the CpG island methylation status in the GBGT1 promoter region demonstrated high or intermediate levels of GBGT1 DNA methylation in all ovarian cancer cell lines (except for OVCAR3) but marginal levels of DNA methylation in the two HOSE cell lines." (PMID 25294702, 2014). "The present study is therefore not only the first one addressing GBGT1 expression and its regulation in ovarian cancer but also suggest that GBGT1 is differentially expressed in cancer and healthy conditions i.e. lower in ovarian cancer patients and higher in normal cells." (PMID 25294702, 2014). "Given that elevated HPA staining is a result of increased GBGT1 expression and that HPA staining is a determinant for poor prognosis also in ovarian cancer, we would expect increased GBGT1 expression in cancer cells." (PMID 25294702, 2014). "GBGT1 was highly expressed in both HOSE cell lines (HOSE6-3 ΔCq = 8.86; HOSE17-1 ΔCq = 8.00) and in the OVCAR3 ovarian cancer cell line (ΔCq = 8.74) but expressed at low levels in the remaining cell lines (ΔCqs ranging from 14.44-14.99)." (PMID 25294702, 2014). "The comparison of the two normal cell lines (HOSE6-3 and HOSE17-1) with the panel of ovarian cancer cell lines (TOV112D, TOV21G, SKOV3, OVCAR3, IGROV1 and A2780) revealed a significantly differential GBGT1 expression (P < 0.001)." (PMID 25294702, 2014). "However, our ovarian cancer TCGA dataset analysis did not reveal an association between methylation or expression levels and survival (neither in univariate models nor when age- and stage-adjusted), indicating that GBGT1 methylation or expression levels are not outcome parameters in ovarian cancer." (PMID 25294702, 2014). "We therefore conclude that GBGT1 expression is epigenetically regulated in ovarian cancer but that it is not a prognostic predictor for survival." (PMID 25294702, 2014).
ovarian carcinoma (continued). "RT-qPCR profiling showed high GBGT1 expression in normal ovary surface epithelial (HOSE) cell lines and low GBGT1 expression in all (e.g. A2780, SKOV3) except one (OVCAR3) investigated ovarian cancer cell lines, a finding that was confirmed by Western blot analysis." (PMID 25294702, 2014). "We wondered whether the observed differential GBGT1 methylation pattern, i.e. largely unmethylated GBGT1 in the normal HOSE cells and hypermethylated in ovarian cancer cells, was also found in primary and recurrent ovarian carcinoma and in normal adjacent tissue." (PMID 25294702, 2014). "The observation that GBGT1 expression is lower by trend in ovarian cancer does neither support nor rules out the idea that the HPA-staining may be a prognostic determinant in ovarian cancer." (PMID 25294702, 2014). "Our results show that GBGT1 is the most variably expressed gene among the Fs-relevant glycogenes and among the investigated cell lines, DNA methylation is involved in the regulation of GBGT1 expression in ovarian cancer cell lines and tissue, and GBGT1 expression does not predict survival." (PMID 25294702, 2014).
GBGT1 also shares sentences with these, for which no sentence is quoted: cancer (2 papers); Herpes simplex infection (1); leprosy (1); ovarian tumor (1).